PYGB (glycogen phosphorylase B)
Description:
Glycogen phosphorylase that regulates glycogen mobilization. Phosphorylase is an important allosteric enzyme in carbohydrate metabolism. Enzymes from different sources differ in their regulatory mechanisms and in their natural substrates. However, all known phosphorylases share catalytic and structural properties.
Synonyms: GPBB
Tractability: Small molecule: a structure with a bound ligand is known. Antibody: its Gene Ontology location is reachable by antibodies, with high confidence. PROTAC: ubiquitination databases record sites on it; its protein half-life has been measured; a small molecule that binds it is known.
Target class: Enzyme; Transferase
Gene: Protein-coding gene on chromosome 20 (25,248,030 to 25,298,014, forward strand). Ensembl gene ENSG00000100994.
Subcellular location (Human Protein Atlas): Cytosol
Pathways (Reactome):
Immune System: Neutrophil degranulation
Metabolism: Glycogen breakdown (glycogenolysis)
Gene Ontology:
Molecular function: 1,4-alpha-oligoglucan phosphorylase activity; protein binding; glycogen phosphorylase activity; pyridoxal phosphate binding
Biological process: glycogen catabolic process; carbohydrate metabolic process
Cellular component: cytoplasm; extracellular exosome; membrane; azurophil granule lumen; cytosol; extracellular region
Genetic constraint (gnomAD): Loss-of-function variants: 85 observed, 99.7 expected, observed/expected ratio (o/e) 0.85, 90% interval 0.71 to 1.02. The upper end of that interval is the gene's LOEUF score, 1.02, which puts it in group 4 of 6, group 1 being the genes least tolerant of losing a copy. Missense variants: 1,128 observed, 1,172.6 expected, observed/expected ratio (o/e) 0.96, 90% interval 0.92 to 1.01. Synonymous variants: 488 observed, 483.79 expected, observed/expected ratio (o/e) 1.01, 90% interval 0.94 to 1.09.
Homologues: Orthologues: chimpanzee PYGB (100% identical), mouse Pygb (96% identical), dog PYGB (95% identical), guinea pig PYGB (94% identical), macaque PYGB (94% identical), rabbit PYGB (92% identical), rat Pygb (91% identical), pig PYGB (91% identical), tropical clawed frog pygm (88% identical), zebrafish pygb (87% identical), Drosophila melanogaster Glyp (72% identical), Caenorhabditis elegans pygl-1 (68% identical). Paralogues in human: PYGM (84% identical), PYGL (81% identical).
Diseases named in the same sentence as PYGB in open-access papers:
PYGB is named in the same sentence as 61 diseases in open-access papers, as found by Europe PMC text mining. Sharing a sentence is not in itself a finding about the gene and the disease. The quoted sentences say what the papers report.
ovarian carcinoma (14 papers, 2018 to 2025). A malignant neoplasm originating from the surface ovarian epithelium. "In previous literatures, PYGB have been reported to be upregulated in ovarian cancer and hepatocellular carcinoma, and this dysregulation promotes ovarian cancer cell and hepatocellular carcinoma cell proliferation, invasion, migration and drug resistance." (PMID 40458414, 2025). "In terms of the mechanism, the results showed that miR-133a-3p targeted PYGB and combined with the 3′-UTR of PYGB to inhibit the development of ovarian cancer." (PMID 38334681, 2024). "Xenograft tumor formation further demonstrated that the knockdown of the PYGB gene significantly inhibited the proliferation, invasion, and migration of ovarian cancer cells, suppressing ovarian cancer tumorigenesis." (PMID 38334681, 2024). "Studies have shown that the high expression of PYGB in ovarian cancer is positively correlated with a poor prognosis for ovarian cancer patients." (PMID 38334681, 2024). "Mechanistically, PYGB is targeted by miR-133a-3p, and an indirect correlation between miRNA and enzyme is present in ovarian cancer samples." (PMID 35348905, 2022). "The upregulation of glycogen phosphorylase B (PYGB) was detected in ovarian cancer tissues, while PYGB knockdown suppressed ovarian cancer cells proliferation, invasion and migration." (PMID 33391416, 2021). "Elsewhere, PYGB was also reported to be upregulated in numerous tumors, including gastric cancer, lung cancer, ovarian cancer, and renal cell cancer." (PMID 34925508, 2021). "PYGB clearly promoted ovarian cancer cell proliferation, invasion and migration via the wnt pathway." (PMID 32880385, 2020). "Knocking down PYGB also significantly inhibited the expressions of Wnt3a, β-catenin, APC, and Cyclin D1 in ovarian cancer cells, suggesting that, through the Wnt/β catenin signaling pathway, PYGB might regulate the progression of ovarian cancer." (PMID 38334681, 2024). "Indeed, glycogen phosphorylase B (PYGB), the rate-limiting enzyme in glycogenolysis, is involved in various tumors, including ovarian cancer where its levels are upregulated and correlate with poor prognosis." (PMID 35348905, 2022). "High PYGB expression was positively correlated with poor prognosis of ovarian cancer patients." (PMID 33324633, 2020). "In ovarian cancer cells, silencing PYGB inhibited cell proliferation, invasion and migration." (PMID 33324633, 2020). "Emerging evidence hints that PYGB is involved in the tumorigeneses of different types of cancer, such as osteosarcoma, breast cancer, prostate cancer, colorectal cancer, gastric cancer, ovarian cancer, and non-small-cell lung cancer, as well as hepatocellular cancer." (PMID 38334681, 2024). "PYGB is integral to the progression of various cancers, including hepatocellular carcinoma (HCC) and ovarian cancer." (PMID 40458414, 2025). "MiR-133a-3p negatively regulates the expression of PYGB by binding to the 3′-UTR of PYGB and ultimately inhibiting ovarian cancer development via the Wnt/B-catenin signaling pathway." (PMID 38793064, 2024). "Our previous research found that the miR-133a/glycogen phosphorylase B (PYGB) axis can inhibit the occurrence and development of ovarian cancer both in vitro and in vivo." (PMID 35012539, 2022). "For instance, upregulation of PYGB was reported in several cancers, such as colorectal cancer, prostate cancer NSCLC and ovarian cancer." (PMID 33324633, 2020). "Whereafter, up-regulated PYGB expression was reported in several cancers, such as colorectal cancer, prostate cancer, non-small cell lung cancer (NSCLC), ovarian cancer." (PMID 33324633, 2020).
gastric cancer (12 papers, 2014 to 2025). A primary or metastatic malignant neoplasm involving the stomach. "Studies have found that the expression of PYGB in human gastric cancer tissues is significantly elevated and positively associated with the clinical–pathological characteristics of gastric cancer patients." (PMID 38334681, 2024). "In particular, PYGB has been reported to implicated both in tumor progression of gastric cancer through the modulation of Wnt/β-catenin pathway and in the invasion of breast cancer cells." (PMID 35897773, 2022). "Multiple studies have revealed that PYGB is highly expressed in various cancers, including lung cancer, prostate cancer and breast cancer, and PYGB has also been investigated as a diagnostic molecular marker in gastric cancer." (PMID 34229669, 2021). "Glycogen phosphorylase (PYGB), an enzyme involved in glycogen metabolism, has been implicated in various tumorigenic processes, including proliferation, metastasis, and epithelial‐mesenchymal transition in breast, ovarian, and gastric cancer." (PMID 39375892, 2025). "In gastric cancer, PYGB promotes proliferation, invasion, and migration through regulation of the Wnt-β-catenin signaling pathway (Xia, Zhang & Liu, 2020)." (PMID 41180485, 2025). "The expression level of PYGB in intestinal-type gastric cancer is significantly higher than that in the diffuse type." (PMID 38334681, 2024). "For example, PYGB promotes the proliferation and migration of non-small cell lung and gastric cancer by activating the Wnt pathway." (PMID 38483604, 2024). "PYGB is important in some cancer cell lines such as pancreatic, prostate, ovary and gastric cancer cells, and for wound healing, invasion and metastasis in breast cancer cell lines." (PMID 35764612, 2022). "PYGB was first found to be highly expressed in gastric cancer cells and localized in the nucleus." (PMID 38334681, 2024). "Thus, patients with stage I, II, III, and IV stomach cancer have significantly higher overexpression of PYGB (p = 0.043), TNF (p = 0.02), HLA-A (0.05), and EFNB2 (0.001) genes, respectively." (PMID 33828156, 2021). "In the gastric cancer cell line SNU16, the protein KIAA1199 upregulates PYGB activity, enhances cell glycogenolysis, and promotes cell proliferation." (PMID 38334681, 2024). "In conclusion, we observed high expression levels of KIAA1199 mRNA in clinical gastric cancer tissue and demonstrated that KIAA1199 protein interacted with PHKB and PYGB in TU-KATO III cell lines." (PMID 25051373, 2014). "Several reports have demonstrated that glycogen phosphorylase brain form (PYGB) is overexpressed in various cancer tissues, including gastric cancer." (PMID 25051373, 2014). "In addition, a strong correlation was seen between the expression of PYGB and both gastric cancer and intestinal metaplasia, whereas no positive staining was observed for PYGB in normal gastric epithelial cells." (PMID 25051373, 2014).
hepatocellular carcinoma (8 papers, 2015 to 2025). A malignant tumor that arises from hepatocytes. "To further investigate the role of AMPK in AR mutation-driven hepatocarcinogenesis, we suppressed the expression of PYGB and SREBP1, two key downstream targets of AR mutations, using siRNA in hepatoma cells." (PMID 38182647, 2024). "In hepatocellular carcinoma (HCC), miR-101-3p was demonstrated to suppress glycogen phosphorylase B (PYGB) expression posttranscriptionally to finally decrease cell proliferation, migration, and invasion." (PMID 36304962, 2022). "Previous studies indicated the high expression of PYGB in hepatocellular carcinoma (HCC) tissues." (PMID 33324633, 2020).
prostate carcinoma (8 papers, 2020 to 2025). A carcinoma that arises from epithelial cells of the prostate gland. "PYGB encodes glycogen phosphorylase which metabolizes glycogen and is reported as an upregulated gene in prostate cancer tissues." (PMID 37612283, 2023). "According to the clinicopathological data, the researchers showed that the expression level of PYGB in prostate cancer tissues was significantly enhanced." (PMID 38334681, 2024). "PYGB silencing suppressed the growth and promoted the apoptosis of prostate cancer cells by affecting the NF-κB/Nrf2 signaling pathway." (PMID 37612283, 2023). "Interestingly, PYGB is highly expressed in various cancers, such as ovarian cancer, glioblastoma, prostate cancer, and non-small cell lung cancer." (PMID 38483604, 2024). "In addition, they also demonstrated that the expression of PYGB was related to the malignancy degree of the prostate cancer." (PMID 38334681, 2024). "Prostate cancer cell growth is suppressed by PYGB inhibition through the NF-κB pathway." (PMID 38483604, 2024). "PYGB knockdown inhibited cell proliferation in human osteosarcoma cell lines, and suppressed cell growth and promotes the apoptosis of prostate cancer cells." (PMID 33324633, 2020). "In short, PYGB is upregulated in prostate cancer tissue and related to disease progression, suggesting that it may become an important target for the pathological diagnosis and treatment of prostate cancer and a prognostic indicator." (PMID 38334681, 2024). "The analysis of the clinicopathological data also confirmed that PYGB was related to the differentiation degree and TNM stage of the prostate cancer tissues." (PMID 38334681, 2024).
breast carcinoma (7 papers, 2019 to 2025). "Inhibition of PYGB expression resulted in decreased glycogen utilization, wound-healing capability, and invasive potential of breast cancer cells." (PMID 33324633, 2020). "In the two breast cancer cell lines, MDA-MB-231 and MCF-7, loss of the brain isoform PYGB inhibited hypoxic glycogen usage whereas the loss of both PYGL and PYGB in the normal-like MCF-10A cell line exhibited this effect." (PMID 31536495, 2019). "They found that knocking down PYGB inhibited the utilization of glycogen in breast cancer cells." (PMID 38334681, 2024). "Thus, we identify PYGB as a novel metabolic target with potential applications in the management and/or prevention of metastasis in breast cancer." (PMID 31536495, 2019). "As early as 2002, the differential expression of PYGB was confirmed, and PYGB was found to be downregulated in HER2/neu-positive breast cancer cells both in vitro and in vivo." (PMID 38334681, 2024). "Regardless of the mechanism of hypoxic glycogen accumulation, we successfully inhibited glycogen utilization in breast cancer using shRNA knockdown of the glycogen phosphorylase isoforms PYGL and PYGB." (PMID 31536495, 2019).
lung cancer (7 papers, 2020 to 2025). A malignant neoplasm involving the lung. "Additional studies suggest that the heightened expression of PYGB in lung cancer may be linked to smoking-related genetic alterations, particularly in LUSC, where PYGB may function as a biomarker associated with smoking." (PMID 40458414, 2025). "Nonetheless, a thorough analysis connecting PYGB expression with lung cancer prognosis, immune cell infiltration, or its therapeutic implications remains absent." (PMID 40458414, 2025). "This study aims to fill this gap by examining the role of PYGB in lung cancer progression and its interactions with the tumor immune microenvironment, thereby proposing PYGB as a novel biomarker and potential therapeutic target." (PMID 40458414, 2025). "While PYGB expression has been documented in various tumor types, its specific function in lung cancer (LC) remains to be elucidated." (PMID 40458414, 2025). "This suggests that PYGB may play a similar role in lung cancer as it does in other cancers, acting as a potential molecular therapeutic target." (PMID 40458414, 2025). "This may suggest that PYGB plays a key role in the tumor immune infiltration microenvironment in lung cancer." (PMID 40458414, 2025). "For lung cancer, we select five essential genes, such as PYGB, C4BPA, SESN3, MMP10, IRS1." (PMID 33133130, 2020). "This suggested that PYGB might play a central role in shaping the tumor immune infiltration microenvironment in lung cancer, potentially highlighting its role as a therapeutic target for immunomodulatory strategies, and that further studies were needed to clarify the relationship." (PMID 40458414, 2025). "Intersection analysis identified core COPD–lung cancer genes (UBA7, ZDHH5, GMPPB, IREB2, PYGB), with emphysema‐specific IREB2 (lung) and PSMA4 (blood)." (PMID 41377765, 2025). "Here, we found that mRNA expression levels of PYGB were enhanced in tumor tissues such as HCC, prostate adenocarcinoma (PRAD), colon cancer (COAD), lung cancer (LUAD) and lung squamous cell carcinoma (LUSC), consistent with the results reported by previous studies." (PMID 33324633, 2020). "The negative correlation of PYGB with these CD4+ T cell subsets might indicated a suppression of helper T cell functions, which could impair the overall immune response to lung cancer." (PMID 40458414, 2025).
myocardial ischemia (5 papers, 2021 to 2024). A disorder of cardiac function caused by insufficient blood flow to the muscle tissue of the heart. "PYGB is thus a good early marker reflecting myocardial ischemia in the pathological process of coronary artery disease." (PMID 38334681, 2024). "For emergency CABG patients, because the half-life of PYGB is shorter than that of CK-MB activity, PYGB is more suitable than CK-MB in the perioperative laboratory monitoring of myocardial ischemia in patients undergoing emergency CABG." (PMID 38334681, 2024). "Previous studies have demonstrated that compound 1 had excellent inhibitory activity against PYGB, highlighting its potential therapeutic effect on myocardial ischemia." (PMID 36234871, 2022). "As the direct evidence of myocardial ischemic injury, its release mainly depends on myocardial ischemia and hypoxia, determining the PYGB mass concentration as a sensitive marker of perioperative myocardial injury in patients undergoing coronary artery bypass grafting." (PMID 38334681, 2024). "According to the research of Dobric and his colleagues, the PYGB plasma concentration increased in 46 patients with known coronary anatomies undergoing an exercise stress echocardiography test (ESET), and it was not related to inducible myocardial ischemia but to the exercise load/duration." (PMID 38334681, 2024).
non-small cell lung carcinoma (5 papers, 2020 to 2024). A group of at least three distinct histological types of lung cancer, including non-small cell squamous cell carcinoma, adenocarcinoma, and large cell carcinoma. "The survival analysis showed that the PYGB expression was associated with the prognoses of patients with non-small-cell lung cancer, and that patients with high PYGB expressions had poor prognoses." (PMID 38334681, 2024). "Not only PYGM, but also PYGB level is up-regulated in different kinds of cancer such as colorectal cancer, hepatocellular carcinoma, prostate cancer, non-small cell lung cancer (NSCLC), and ovarian cancer." (PMID 33924466, 2021). "Interestingly, increased expression of PYGB has been reported in several cancers, such as ovarian cancer, hepatocellular carcinoma, colorectal cancer, prostate cancer and non-small cell lung cancer." (PMID 35897773, 2022). "In addition, Zhan at al. showed that PYGB activates the PI3k/Akt signaling pathway and, therefore, the tumorigenesis of non-small cell lung cancer." (PMID 35897773, 2022).
glioblastoma (4 papers, 2021 to 2025). The most malignant astrocytic tumor (WHO grade IV). "In conclusions, our research highlights PYGB as a potential therapeutic target in GBM proposing 1g as a lead compound for developing a new class of simplified analogs active as anticancer drugs for glioblastoma, keeping unchanged its ability to cross the blood–brain barrier." (PMID 35897773, 2022). "The 1g main target in the glioblastoma U87MG cells lysate is a receptor called Glycogen Phosphorylase, brain form (PYGB, also named GPBB)." (PMID 35897773, 2022). "The results highlighted PYGB as a potential therapeutic target for U87MG of GBM and indicated that 2,3-benzodiazepin-4-one can be used to develop anti-cancer drugs for glioblastoma because it can negatively regulate glucose uptake and metabolism (the “Warburg effect”)." (PMID 38334681, 2024). "However, experimental data of bevacizumab treatment suggest that, unlike PYGL, neither PYGM or PYGB exhibited a detectable increase in U87 (glioblastoma) cells." (PMID 34177761, 2021).